NF2 (NF2, moesin-ezrin-radixin like (MERLIN) tumor suppressor)
Diseases named in the same sentence as NF2 in open-access papers (continued):
Sharing a sentence is not in itself a finding about the gene and the disease.
mesothelioma (continued). "Mutations in the NF2 gene have been found in about 40% of human mesothelioma, and the influence of Nf2 heterozygosity has been investigated in mice; Nf2 heterozygosity was shown to result in MM at high frequency (85%) within 1 yr after repetitive asbestos exposure." (PMID 25877069, 2015). "The tumor suppressor gene NF2 is one of the most frequently mutated genes in human mesothelioma, but its detailed function is still unknown." (PMID 25877069, 2015). "Mutations in known mesothelioma-related genes NF2, CDKN2A, LATS2, amongst others, were identified." (PMID 25798586, 2015). "By MLPA assay, array-CGH analysis, and NGS on blood and tumor DNA, we determined the mutation profile of this rare NF2-driven PM and we identified several atypical chromosomal aberrations in tumor cells, suggesting a different genomic signature between pediatric and adult mesothelioma." (PMID 40725095, 2025). "In addition to FAK, the discovery of new molecules or drugs that can induce synthetic lethal phonotype with NF2 deficiency may provide a new therapeutical strategy for mesothelioma." (PMID 37180489, 2023). "NF2 mRNA was reported to have splicing variants, and the same study indicated that the carboxyl-terminal variant (isoform 2), which may not have tumor suppressive activity, is more significantly expressed in mesothelioma." (PMID 37180489, 2023). "Fifteen of the NF2 missense variants included in this study were observed exclusively in somatic samples from non‐NF2 related tumors, and this is consistent with previous observations of somatic NF2 variants in multiple cancer types, such as mesothelioma, liver, and large instestine cancers." (PMID 35332608, 2022). "Furthermore, co-inactivation of LATS2 and NF2 in mesothelioma cell lines triggers the loss of cell–cell contact inhibition, dysregulation of Hippo and mammalian target of rapamycin (mTOR) signalling, and correlates with higher sensitivity to inhibitors of the PI3K–AKT–mTOR pathway." (PMID 34226685, 2021). "Here, we take the opportunity of our recent study in asbestos-exposed C57Bl/6J Nf2+/− mice, to identify lncRNAs and miRNAs associated with tumor development and scrutinize their expression and heterogeneity in human mesothelioma and human mesothelioma TCGA RNAome." (PMID 29641489, 2018). "Mesothelioma has characteristic genetic changes including inactivation of neurofibromatosis type 2 (NF2) and deletion of the INK4A/ARF region." (PMID 41729969, 2026). "Together, NF2 loss, YAP1 amplification, and LATS1/2 inactivation highlight the central role of this pathway in mesothelioma." (PMID 40362535, 2025). "Genomic studies have revealed that mesothelioma is predominantly characterized by loss-of-function alterations in tumor suppressor genes, with mutations in CDKN2A, BAP1, and NF2 being the most frequently observed." (PMID 41463232, 2025). "Supporting this model, mesothelioma patients with low levels of NF2 showed a decreased YAP_pS127 expression across two independent cohorts." (PMID 40707702, 2025). "Recently, VT3989, a TEAD inhibitor targeting the Hippo-YAP pathway, was well tolerated and demonstrated promising antitumor activity, including partial responses, in patients with mesothelioma and NF2-mutant tumors." (PMID 40362535, 2025). "Several molecular targeted therapies have been explored for mesothelioma, particularly those aimed at tumors harboring NF2 alterations." (PMID 41463232, 2025).
mesothelioma (continued). "Primary pericardial mesotheliomas are extremely rare, accounting for <1% of all mesotheliomas, and they share similar genomic aberrations with peritoneal mesotheliomas, being driven by several genes including NF2." (PMID 40725095, 2025). "In a first-in-human Phase I trial (NCT04665206) for advanced solid tumors enriched with NF2-mutant mesothelioma patients, VT3989 has demonstrated a tolerable safety profile and preliminary antitumor activity." (PMID 40612350, 2025). "In asbestos-induced mesotheliomas, CDKN2A mutations often occur after biallelic inactivation of NF2, another key tumor suppressor gene." (PMID 40362535, 2025). "Genes of the Hippo pathway, which appears to be a significant signaling pathway regulated by merlin in mesothelial cells, are frequently inactivated in mesotheliomas in addition to NF2." (PMID 40227645, 2025). "For example, the YAP inhibitor IAG933 induced deep tumor regression in NF2-altered mesothelioma models." (PMID 40174508, 2025). "The immune cell composition in BNC closely resembles that in human mesothelioma with BAP1, NF2, and CDKN2A loss—M2 macrophages, T cells, and B cells make up a significant proportion of the leukocyte population." (PMID 38879686, 2024). "This is conceptually consistent with a previous report that NF2 mutant mesothelioma cells are sensitive to ferroptosis." (PMID 38879607, 2024). "These MPM tumor cells highlighted a different pathway involved in the tumorigenesis of NF2-mutant mesothelioma." (PMID 39796693, 2024). "Lastly, JM7 was found to preclinically inhibit YAP transcriptional reporter activity in NF2‐mutant mesothelioma cells." (PMID 38606782, 2024). "In mesothelioma cells, NF2 expression was found to be significantly downregulated in all tested conditions apart from 12 h of CT with Pt(IV)Ac-POA, and the signal was localized mainly in the cytoplasm." (PMID 39204360, 2024). "In a recent clinical trial (NCT04665206), the TEAD inhibitor VT3989 garnered attention for its antitumor efficacy in advanced mesothelioma and NF2-mutant cancers." (PMID 38067201, 2023). "Future studies are needed to more precisely identify the roles of merlin (NF2) alteration in mesothelioma development and progression, which would lead to the development of new molecular-targeted drugs." (PMID 37180489, 2023). "A recent study indicated that the addition of genetic NF2 screening improved the sensitivity or specificity of mesothelioma diagnosis." (PMID 37180489, 2023). "Recent genome analysis with multi-sampling of the same patient’s mesothelioma tissues revealed clonality of mesothelioma cells, which showed that BAP1/3p21 loss is an early event, while NF2/22q loss is a late event." (PMID 37180489, 2023). "We recently described new mouse models of mesothelioma where Bap1 deletion accompanied with alterations in genetic drivers Nf2 and Cdkn2ab results in fast and aggressive mesothelioma." (PMID 36657447, 2023). "Regarding NF2, whole-exome sequencing alone cannot detect translocation and large deletion of NF2, which occasionally happens in mesothelioma." (PMID 37180489, 2023). "The significance of Nf2 inactivation in mesothelioma pathogenesis was confirmed in Nf2-knockout mouse models in vivo." (PMID 37180489, 2023). "It has been observed that all mesothelioma cell lines have lost their heterozygosity due to neurofibromatosis type 2 (NF2)." (PMID 37469419, 2023). "The observation that deletion of P16INK4A, P14ARF, and NF2 are the most common irregularities suggests that mesothelioma growth requires a specific sequence of tumour suppressor gene deletion." (PMID 37469419, 2023). "While NSCLC is characterised by activating mutations in oncogenes, mesothelioma on the other hand is characterised by the frequent inactivating alteration of the CDKN2A, NF2 and BAP1 tumour-suppressor genes." (PMID 38015374, 2023).
mesothelioma (continued). "Conditional knockout mice targeting Nf2, Bap1, and/or Cdkn2a in cells of the mesothelium exhibited an increased incidence of mesothelioma, and noticeably, the triple-knockout mice showed highly invasive tumors with the shortest survival times." (PMID 37180489, 2023). "Similar dose dependent effect on decrease of CTGF and CYR61 transcript levels were also observed in NF2 mutant NCI-226 mesothelioma cells." (PMID 36523977, 2022). "In all three of these trials, the primary disease being targeted is NF2-mutant mesothelioma and other NF2-mutant solid tumors." (PMID 35740643, 2022). "In our previous studies, we showed that an increase in A‐to‐I RNA editing occurs during the development of mesothelioma in a Neurofibromatosis+/− (Nf2+/−) mouse model." (PMID 36221913, 2022). "These compounds showed significant anti-tumor effects in NF2-mutant mesothelioma cells, while having limited effects on other YAP/TAZ-dependent cancer cell lines." (PMID 36347861, 2022). "Our analysis shows frequent mutations and deletions of NF2 in TCGA KIRC (kidney renal clear cell carcinoma), KIRP (kidney renal papillary cell carcinoma) and MESO (mesothelioma) cohorts." (PMID 35975235, 2022). "Their work has shown how mesotheliomas mostly follow a linear evolution with BAP1 being the most frequent ancestral mutation and NF2 arising mainly as a late event." (PMID 35204459, 2022). "Of the few studies on targeted drugs that include mesothelioma, most late-stage studies are focused on BAP1 mutations while inactivating NF2 mutations (and other hippo pathway mutations) are more prevalent in pleural mesothelioma patients." (PMID 34621176, 2021). "To date, there are no studies demonstrating the correlation between SETDB1 and the three most frequent mutated genes (BAP1, NF2, and CDKN2A) in mesothelioma." (PMID 34299035, 2021). "preclinical in vivo studies have shown the central role of NF2 in sensitizing tissue to asbestos and developing mesothelioma." (PMID 34249695, 2021). "A previous study using NF2 and p16 double-knockout (DKO) mice indicated that these genes, when mutated, contribute to mesothelioma development." (PMID 33298865, 2020). "For mesothelioma, the top genes with mutations were BAP1 (BRCA-associated protein 1), NF2 (neurofibromin 2), and SETD2 (SET domain containing 2, histone lysine methyltransferase)." (PMID 32033319, 2020). "In mice combinatorial deletions of Bap1, Nf2, and Cdkn2a result in aggressive mesotheliomas, defined by stem cell-like potential." (PMID 32392897, 2020). "In two mesothelioma cell lines [MSTO-211H (LATS2 mutation) and H2373 (NF2 mutation)] and RPE1 cells, survival was significantly reduced at 72 hours after YAP/TAZ siRNA transfection." (PMID 32277165, 2020). "Of note, YAP1/TAZ activation has been previously shown to confer malignant phenotypes to mesothelial cells and conditional (mesothelium-specific) NF2 knockout mouse models exhibited an increased incidence of mesothelioma development." (PMID 31959902, 2020). "NF2 transcripts undergo alternative splicing, thereby generating multiple isoforms, and variable NF2 transcripts are observed in human mesotheliomas." (PMID 29587439, 2018). "These in vitro and in vivo data strongly support the role of NF2 inactivation in mesothelioma development." (PMID 29587439, 2018). "This region, along with 22q12 containing the NF2 gene, which is inactivated in mesotheliomas, was also lost in our patient's tumor." (PMID 27403364, 2016).
mesothelioma (continued). "It is also possible that differential gene alterations (such as loss or mutation of NF2 or BAP1) can also contribute to metabolic changes and altered mitochondrial morphologies in mesothelioma and should be more thoroughly investigated." (PMID 27080907, 2016). "The most common genetic alterations associated with mesothelioma, including CDKN2A deletions and NF2 mutations, have been known for about two decades." (PMID 25952750, 2015). "Mesothelioma cell lines were useful tools to demonstrate that the NF2 tumour suppressor gene product, merlin, exerts its anti-proliferative effect in mesothelioma by suppression of p21 activated kinase-induced cyclin D1 expression." (PMID 23516439, 2013). "About 70–80% of mesothelioma specimens possess deficiency in the INK4A/ARF locus containing p16 INK4A and p14 ARF genes, about 40% in neurofibromatosis type 2 gene (NF2) and about 10% in BRCA1 associated protein-1 (BAP1) gene." (PMID 23484132, 2013). "Mesotheliomas develop following exposure, by intraperitoneal injection, of hemizygous NF2 mice to asbestos fibres." (PMID 19523217, 2009). "Because heterozygous Nf2+/− mice exposed to crocidolite develop malignant mesothelioma at a faster rate than wild-type littermates, this mouse model could be used as an ideal and relatively rapid animal model to study the potential of SWCNTs to cause mesothelioma." (PMID 18795165, 2008). "It has been suggested that NF2-SWN patients could be at increased risk of developing mesothelioma, but, actually, patients with inherited NF2-SWN rarely develop mesothelioma as a second cancer and the few reported cases all happened in adult age." (PMID 40725095, 2025). "The lack of reports of an elevated risk of mesothelioma among carriers of NF2 germline mutations supports this theory." (PMID 40227645, 2025). "Moreover, the authors elegantly show that DHODH inhibitors elicit robust antitumor activity against NF2-altered mesothelioma and exhibit strong synergy with cisplatin, opening a new translational avenue for this tumor subtype." (PMID 40707701, 2025). "In adults, NF2 inactivation in mesothelioma cells is considered a late event that may result in an aggressive phenotype." (PMID 40725095, 2025). "Similarly, in mesothelioma cells with inherent NF2 deletions, DHODH inhibition led to a notable reduction in tumor growth." (PMID 40707702, 2025). "More broadly, this study highlights the need for further research into NF2-driven metabolic dependencies in other cancer types, which could potentially broaden therapeutic strategies beyond mesothelioma." (PMID 40707702, 2025). "There have been reports of splicing variations in NF2 mRNA, and the same study found that mesothelioma has higher levels of expression of the carboxyl-terminal version (isoform 2), which may not have a tumor suppressive function." (PMID 40227645, 2025). "Studies with pharmacologic inhibitors reveal YAP/TEAD dependency in cancers with HIPPO pathway mutations (such as mesotheliomas with NF2 loss) but not more broadly, even in tumors with robust YAP/TEAD activation." (PMID 41509338, 2025). "The most commonly inactivated tumor suppressor genes in mesothelioma are NF2, BAP1, and CDKN2A." (PMID 40362535, 2025). "It is conceivable that brequinar could display improved safety and efficacy when specifically deployed against NF2-altered mesothelioma." (PMID 40707701, 2025). "SW-682 is currently being studied in a phase I clinical trial for individuals with mesothelioma with or without NF2 mutations (NCT06251310)." (PMID 41375064, 2025). "The study included 172 patients, 135 of whom had heavily pretreated mesothelioma regardless of NF2 mutational status." (PMID 41375064, 2025). "Here we propose that in pediatric mesothelioma NF2 inactivation could instead represent an early driver event." (PMID 40725095, 2025).
mesothelioma (continued). "Moreover, both commercial mesothelioma cell lines and primary patient-derived cells (PDCLs) with inherent NF2 deficiency exhibited greater sensitivity to DHODH inhibition compared to NF2-intact counterparts (I and EV4J–M)." (PMID 40707702, 2025). "Three of the most frequent clonal genetic alterations that occur in human mesothelioma cells are somatic mutations and deletions of the tumor suppressor genes BAP1, CDKN2A/B, and NF2, and germline mutation of BAP1 is a well-established genetic risk factor for mesothelioma." (PMID 38784478, 2024). "YAP/TAZ-TEAD inhibition triggered tumor regression in preclinical mouse models for mesothelioma and first data report clinical benefits for mesothelioma patients and patients with NF2 mutant sarcoma: ION537 (NCT04659096), VT3989 (NCT04665206), IK-930 88 NCT05228015) and IAG933 (NCT04857372)." (PMID 38538573, 2024). "From those 7 responders, 6 had refractory mesothelioma (two NF2 mutant, three NF2 wild type and one unknown) and 1 had an NF2 mutant sarcoma." (PMID 38538573, 2024). "Moreover, a significant fraction of mesothelioma tumors have cytogenetic abnormalities in chromosome 22, where NF2 is located." (PMID 39796693, 2024). "In early clinical trials, these drugs, along with inhibitors that directly block YAP-TEAD interactions, have been found to be well tolerated and show antitumor activity in NF2-mutant cancers and mesothelioma, a condition known to often have NF2 alterations (NCT04665206, NCT05228015, NCT04857372)." (PMID 39083549, 2024). "A number of selective inhibitors of the TEAD family members are in development and have been shown to disrupt YAP1/WWTR1/TEAD-dependent transcription, affect the viability of NF2 mutant mesothelioma models, and to enhance the efficacy of EGFR inhibitors in EGFR mutant lung cancer." (PMID 38658677, 2024). "First, to compare the potency and selectivity of the TEADi(s), we performed live-cell proliferation assays (Incucyte) in two NF2 defective mesothelioma cell lines (NCI-H226 and NCI-H2052), using two NF2 wild-type cell lines (NCI-H28 and NCI-H2452) as a compare/contrast selectivity control." (PMID 38139762, 2023). "NF2 alteration is a key genetic change in mesothelioma development, which may occur at a late stage as a subclonal event, suggesting that NF2 alteration may not be directly induced by asbestos exposure." (PMID 37180489, 2023). "Moreover, CRL4DCAF1 was shown to directly bind to LATS1/2 and induce their ubiquitination and degradation; thus, upregulated CRL4DCAF1 in NF2-inactivated mesothelioma cells accelerates degradation of LATS1/2 and hence activates YAP." (PMID 37180489, 2023). "The scarcity of actionable mutations in mesothelioma limits the application of targeted drug treatments, and therefore, many trials have focussed on pathways affected by genetic alterations affecting BAP1, CDKN2A and NF2." (PMID 38015374, 2023). "Although the exact role and timing of NF2 inactivation in mesothelioma cells remain to be elucidated, targeting the NF2/merlin-Hippo pathway may be a new therapeutic strategy for patients with mesothelioma." (PMID 37180489, 2023). "Thus, while the roles and timing of NF2 inactivation in mesothelioma cells remain to be fully elucidated, the study of NF2 in mesothelioma is a focus of much research to develop new diagnostic and therapeutic tools against this formidable disease." (PMID 37180489, 2023). "A pilot study of chemotherapy treatment using previously published doses, revealed CNP mice to be extremely sensitive to chemotherapy-induced toxicity, requiring reduction of both drugs to half the concentrations used in mesothelioma mouse model driven by triple deletion of Bap1, Cdkn2a and Nf2." (PMID 37441092, 2023). "A recent study indicated that Nf2; Cdkn2a-deficient mouse mesothelioma cells showed less malignant phenotypes with PAK2 loss, suggesting that anti-PAK drugs may be promising for mesothelioma treatment." (PMID 37180489, 2023).